IL33 (interleukin 33)
Diseases named in the same sentence as IL33 in open-access papers (continued):
Sharing a sentence is not in itself a finding about the gene and the disease.
gram-negative bacterial infections (3 papers, 2015 to 2021). Infections caused by bacteria that show up as pink (negative) when treated by the gram-staining method. "Of note, TLR4 and IL-33 expressions were positively associated with Ki-67 proliferative index (PI) and expressions of CSC-related gene CD133 in NSCLC patients with gram-negative bacterial infection." (PMID 29568370, 2018). "Herein, we extended previous studies by demonstrating that gram-negative bacterial infection led to high expression of IL-33 in NSCLC cells through TLR4 activation." (PMID 29568370, 2018). "In NSCLC patients, higher TLR4 expression was associated with increased IL-33 expression, Ki-67 proliferation index and CD133 expression in those with gram-negative bacterial infection." (PMID 29568370, 2018). "But whether IL-33 is involved in the crosstalk of gram-negative bacterial infection and NSCLC progression, still remains unknown." (PMID 29568370, 2018). "The signals regulating IL-33 expression in the airway epithelium following a gram-negative bacterial infection are currently unknown." (PMID 26793709, 2015). "It has also been reported that in NSCLC patients with gram-negative bacterial infections, the excessive activation of the TLR4/IL-33 axis promotes tumor progression." (PMID 34457117, 2021). "We observed higher TLR4, IL-33 and CD133 expressions in NSCLC patients with gram-negative bacterial infection." (PMID 29568370, 2018).
hay fever (3 papers, 2017 to 2022). "It has been reported that the interleukin-33 SNP rs1888909 is associated with an increased risk of hay fever in high linkage disequilibrium via interaction with rs928413 and rs1342326." (PMID 33770380, 2022). "In relation to pollen allergy and GM-SCF, this cytokine has been reported to increase with IL-33 and IL-25 in animal models, and following the activation of neutrophils and antigen-specific T cells." (PMID 31817806, 2019).
idiopathic pulmonary arterial hypertension (3 papers, 2019 to 2023). A sporadic form of pulmonary arterial hypertension (PAH) characterized by elevated pulmonary arterial resistance leading to right heart failure. "Interleukin-33, the circulating sST2 ligand, was demonstrated in a previous study to potentially contribute to vascular remodeling of the pulmonary endothelium in idiopathic pulmonary arterial hypertension (iPAH)." (PMID 37637518, 2023). "A previous study showed that the circulating ligand of sST2, interleukin-33, may play a role in the vascular remodeling of the pulmonary endothelium in idiopathic pulmonary arterial hypertension (iPAH)." (PMID 31547136, 2019).
infectious colitis (3 papers, 2021 to 2022). A viral or bacterial infectious process affecting the large intestine. "In a model of Citrobacter rodentium-driven infectious colitis, IL-33 inhibited the differentiation of IL-17A-producing CD4+ T cells, which have the potential to reverse the negative effect of IL-33 during infection." (PMID 36570798, 2022).
Infertility (3 papers, 2022 to 2025). "Combined with previous evidence, we hypothesized that the intracellular IL33 in the eutopic endometrium of the infertile women with adenomyosis may cause failure of embryo implantation." (PMID 35937844, 2022). "Estrogens strongly activate IL-17 and IL-33, supporting the existence of a gut–endometrial axis as a significant contributor to infertility." (PMID 39596052, 2024). "The purpose of this study is to confirm the function of intracellular IL33 on embryo implantation and further clarify the mechanism of infertility in adenomyosis." (PMID 35937844, 2022). "In our study, we illustrated that in both the endometrium of infertile women and the mouse model with adenomyosis, IL33 expression was downregulated." (PMID 35937844, 2022). "The ARIA-MeDALL hypothesis, originally linking chronic diseases to dysbiosis and proinflammatory cytokines like IL-17 and IL-33, has recently been extended to infertility, proposing that dysbiosis-driven inflammation and hormonal disruptions may similarly contribute to reproductive challenges." (PMID 39596052, 2024).
interstitial lung disease (3 papers, 2017 to 2022). A diverse group of lung diseases that affect the lung parenchyma. "Beyond this work, few studies have attempted to address the clinical relevance of IL-33 and TSLP expression in the context of IPF or other interstitial lung diseases." (PMID 28202030, 2017). "Cut-off values of 4.66 pg/μg TSLP and 2.52 pg/μg IL-33 possessed 99.4 and 93.2% accuracy for differentiating among the IPF and other interstitial lung disease groups." (PMID 28202030, 2017). "The ROC curves for TSLP and IL-33 demonstrated a clear difference between the IPF and NC groups (TSLP: AUC = 0.655; IL33: AUC = 0.706), as well as among the patients with IPF and those with other interstitial lung diseases (n = 61, TSLP: AUC = 0.786, and IL-33: AUC = 0.781)." (PMID 28202030, 2017). "Our aim was to test whether both IL-33 and IL-13 are higher in patients with diffuse SSc and interstitial lung disease (SSc-ILD) compared to SSc patients without ILD and healthy controls." (PMID 35252259, 2022). "Therefore, our aim was to verify the preliminary hypothesis that both IL-33 and IL-13 are higher in patients with diffuse SSc and interstitial lung disease (SSc-ILD) compared both to SSc patients without ILD, as measured through pulmonary function tests (DLco, TLC, FVC), and to healthy controls." (PMID 35252259, 2022).
intestinal cancer (3 papers, 2019 to 2025). "A recent report from Pastille and colleagues stated that IL-33 enhanced the development of regulatory T lymphocytes, thereby promoting intestinal cancer." (PMID 34504486, 2021). "Recent evidence showed IL-33 to promote tumorigenesis of intestinal cancer by enhancing the accumulation of ST2L+ and FoxP3+ Tregs within the tumor microenvironment." (PMID 34504486, 2021).
laryngeal squamous cell carcinoma (3 papers, 2020 to 2024). A squamous cell carcinoma that arises from the larynx. "In patients with laryngeal squamous cell carcinoma (LSCC), high expression of IL-33 in tumor samples was an unfavorable prognostic factor, with a strong tendency towards statistical significance (p = 0.051)." (PMID 33634017, 2020). "In laryngeal squamous cell carcinoma (LSCC), IL-33 can act as a pro-tumour factor." (PMID 38662248, 2024).
metastasis (3 papers, 2023 to 2025). The spread or migration of cancer cells from one part of the body (where they first appeared) to another. "In some patient cohorts, increased IL-33 expression has been associated with higher tumour grade, lymph node metastasis, and reduced overall survival, suggesting an association with tumour promotion." (PMID 41284319, 2025). "Inducing a local inflammatory milieu by IL-33 administration provided a novel approach for treating peritoneal metastasis, which, when combined with TAM reprogramming to reshape TIME, can achieve better treatment efficacy." (PMID 38238529, 2024).
metastatic carcinoma (3 papers, 2016 to 2024). A carcinoma which has spread from the original site of growth to another anatomic site. "We showed that the intraperitoneal administration of IL-33 was a promising strategy for treating peritoneally confined metastatic cancers." (PMID 38238529, 2024). "Initially, the difference in IL-33 levels within the tumour microenvironment of the primary and metastatic carcinomas was the clue that led us to study ILC2s, whose development and function are strongly dependent on IL-33 expression." (PMID 29440650, 2018). "While many genes were found to be downregulated in metastatic cancer as compared to primary cancer, one gene in particular, IL-33, was selected for further study since it is a key inducer of helper T cells and innate immune cells." (PMID 27619158, 2016). "While we have demonstrated the importance of IL-33 in immune recognition of metastatic cancers in mice, we next tested whether this correlation held true in human clinical samples." (PMID 27619158, 2016). "IL-33 is a strong inducer of MHC-I and antigen processing in metastatic cancers." (PMID 27619158, 2016).
microcephaly (3 papers, 2019 to 2021). A congenital or acquired developmental disorder in which the circumference of the head is smaller than normal for the person's age and sex. "Presence of NLRP1, NLRP3, and AIM2 together with elevated IL-1β, IL-18, and IL-33 could be detected in the brain of ZIKV-infected patients with microcephaly." (PMID 33796483, 2021).
myeloid leukemia (3 papers, 2020 to 2025). A clonal proliferation of myeloid cells and their precursors in the bone marrow, peripheral blood, and spleen. "IL-1RAP is a transmembrane protein that potentiates multiple inflammatory signaling pathways, including IL-1, IL-33, IL-36G, and stem cell factor, and it has the unique feature of being expressed at higher levels in stem and progenitor cells from myeloid leukemia patients compared to normal HSPCs." (PMID 37498674, 2023).
neuropathic pain (3 papers, 2019 to 2024). Chronic pain caused by damage to nerve fibers. "In a separate study, the intrarubral injection of AG490 into the RN after SNI and before IL-33 treatment relieved SNI-induced mono-neuropathic pain and IL-33-evoked mechanical hypersensitivity in male rats." (PMID 37307838, 2024). "In this study, we first found that the expression of DRG IL-33 and ST2 increased in a rat model of neuropathic pain induced by SNI." (PMID 32116550, 2020).
oral cancer (3 papers, 2021 to 2025). "Third IL-33 expression was previously detected in both oral cancer cells and cancer-associated fibroblasts, with a reported association between IL-33 expression levels and patient prognosis." (PMID 41374934, 2025).
osteonecrosis (3 papers, 2021 to 2023). A none disease characterized by death of bone tissue due to a lack of blood supply. "In our study, the IL-33 values in patients with osteonecrosis were very low, thus discounting this marker as an element of early diagnosis and progression of osteonecrosis." (PMID 36969226, 2023). "Plasma IL-33 levels were comparable in 44 patients with sickle cell disease with osteonecrosis of the femoral head as compared with 24 patients with sickle cell disease without ONFH (2.05 ± 4.57 pg/mL versus 1.50 ± 2.89 pg/mL, p-value = 0.590)." (PMID 35371856, 2022). "IL-33 is raised in all of these conditions with ONFH and was recommended for use as a marker for osteonecrosis of the femoral head." (PMID 35371856, 2022). "In recent studies, pro-inflammatory cytokines, interleukin 33 (IL33), and interleukin 17A (IL17A), which are members of the interleukin 1 (IL1) family, play roles in osteonecrosis." (PMID 34305456, 2021). "in India, in which IL-33 plasma levels did not correlate with osteonecrosis of the femoral head in patients with SCD." (PMID 36969226, 2023). "The circulating IL-33 concentration is considered a biomarker of avascular necrosis of the femoral head in patients without SCD, since increased IL-33 levels correlate with osteonecrosis of the femoral head." (PMID 36969226, 2023). "Plasma interleukin-33 levels correlated well with ONFH, but these studies did not mention sickle cell disease as a cause of osteonecrosis." (PMID 35371856, 2022). "Forty-four consecutive patients with sickle cell disease with osteonecrosis of the femoral head and matched controls without ONFH were evaluated for plasma interleukin-33 levels by enzyme-linked immunosorbent assay (ELISA)." (PMID 35371856, 2022). "Plasma IL-33 levels do not correlate with osteonecrosis of the femoral head in patients with sickle cell disease." (PMID 35371856, 2022).
polycythemia vera (3 papers, 2015 to 2023). "In regard to IL-33, the difference between MPNd and MPNn was not significant (p = 0.069), however, when subdivided into subgroups, a significant difference was found between polycythemia vera patients with drusen and those without drusen (p = 0.005)." (PMID 36906669, 2023).
postmenopausal osteoporosis (3 papers, 2019 to 2020). Metabolic disorder associated with fractures of the femoral neck, vertebrae, and distal forearm. "The finding of low levels of IL-33 in postmenopausal osteoporosis is consistent with previous observations suggesting an inhibitory action of IL-33 on osteoclast differentiation." (PMID 32069819, 2020). "In the present study on the contrary, serum levels of IL-33 are lower in postmenopausal osteoporosis compared to age-mached healthy women." (PMID 30846811, 2019). "In our previous studies, based on the IL-31 and IL-33 role in inflammation and bone remodeling we evaluated, their involvement in postmenopausal osteoporosis." (PMID 31798591, 2019). "Moreover, IL-33 could be considered an important bone-protecting cytokine, becoming a target in the prevention and therapy of postmenopausal osteoporosis." (PMID 31798591, 2019).
prediabetes (3 papers, 2019 to 2024). "The association between adipose tissue IL-33 and macrophage markers, including pattern recognition receptors (PRRs) and chemokine receptors, was assessed in individuals with normoglycemia, prediabetes, and T2D." (PMID 31073344, 2019). "The association between adipose tissue IL-33 and inflammatory cytokines and chemokines was evaluated in individuals with normoglycemia, prediabetes, and T2D." (PMID 31073344, 2019). "In contrast, a comparison of IL-33 and ST2 levels across individuals with normoglycemia, prediabetes, and T2D showed an inverse association between IL-33 expression in adipose tissue and overall glycemia, suggesting a potential regulatory role of the IL-33/ST2 axis in glucose homeostasis." (PMID 39171751, 2024). "We determined whether adipose tissue IL-33 was associated with genes involved in beiging of adipose tissue in individuals with normoglycemia, prediabetes, and T2D." (PMID 31073344, 2019). "Interestingly, IL-33 was directly correlated with TLR9 (r = 0.6; P = 0.002; n = 23) in individuals with prediabetes; and comparative analysis confirmed that higher levels of IL-33 were associated with significantly higher TLR9 expression (P = 0.003; median 8.84, n = 15 vs. median 4.6, n = 8)." (PMID 31073344, 2019). "In the present study, we investigated the expression level of IL-33 (and ST2) in the adipose tissue, as well as its association with various immune and metabolic parameters, in individuals with normoglycemia, prediabetes, and T2D." (PMID 31073344, 2019). "Since prediabetes is an early-stage metabolic disorder which, if left unmanaged, often progresses to T2D, one would have expected to observe a similar dynamic between IL-33/ST2 and HbA1c among individuals with prediabetes and T2D; however, this was not the case." (PMID 31073344, 2019). "Adipose tissue IL-33 was inversely associated with HbA1c in individuals with normoglycemia and T2D but not in those with prediabetes and was inversely correlated with fasting plasma glucose in individuals with T2D and with a better glycemic control." (PMID 31073344, 2019). "Interestingly, however, a direct association was observed between IL-33 and IL-12A in individuals with T2D but not in those with normoglycemia or prediabetes." (PMID 31073344, 2019). "Furthermore, exogenous administration of IL-33 to individuals with prediabetes (and/or T2D) may promote reversal of metabolic derangement." (PMID 31073344, 2019). "Given the importance of IL-33/ST2 axis in protection against metabolic disease, we sought to investigate whether IL-33 was differentially associated with ST2 among individuals with normoglycemia, prediabetes, and T2D." (PMID 31073344, 2019). "Therefore, we investigated the expression level of IL-33 (and ST2) in the adipose tissue, as well as its association with overall glycemia (measured by HbA1c), mediators of inflammation and immune regulation, and beiging of adipose tissue, among individuals with normoglycemia, prediabetes, and T2D." (PMID 31073344, 2019). "Out of all the TLRs tested, IL-33 was directly correlated with TLR3 and TLR9 in individuals with T2D and prediabetes, respectively." (PMID 31073344, 2019). "Accordingly, IL-33 was directly associated with PRDM16 but not with UCP1 or COX7A1 in individuals with normoglycemia and T2D but not in those with prediabetes." (PMID 31073344, 2019). "We found a direct association between IL-33 and CD302 in individuals with normoglycemia and T2D but not in those with prediabetes." (PMID 31073344, 2019). "Our data showed that IL-33 was directly associated with ST2 in individuals with normoglycemia and T2D but not in those with prediabetes." (PMID 31073344, 2019). "IL-33-to-ST2 ratio was inversely correlated with HbA1c in individuals with normoglycemia but not in those with prediabetes or T2D." (PMID 31073344, 2019).